TNF (tumor necrosis factor)
Diseases named in the same sentence as TNF in open-access papers (continued):
Sharing a sentence is not in itself a finding about the gene and the disease.
infection (continued). "We measured pro-inflammatory cytokine response (TNF-α, IFN-γ, IL-1β, and IL-6) in the lungs of untreated or EtOH-treated mice and uninfected or infected with Ab at 4, 24, 48, and 72 h post-infection." (PMID 24752133, 2014). "Our score system, based on the most characterized M1 and M2 markers (TNFα and IL10, respectively), showed that MΦs from all patients suffering from a subsequent infection exhibited an evident M2 phenotype." (PMID 24797663, 2014). "Homogenates of kidneys from CD11cΔSyk mice showed higher levels of IL-6, KC, MIP-1α, IL-1β, TNF, IL-1α and MCP-3 at days 1 or 2 post-infection when compared to control mice." (PMID 25033445, 2014). "We confirmed that anti-TNF-α and anti-IL-1β neutralizing antibodies inhibited the effect of recombinant TNF-α and IL-1β on HCVpp infection." (PMID 24259385, 2014). "The results showed that the expression level of NLRP3, IL-1β and TNF-α changed in the lung and brain of BALB/c mice after infection by VK627 and rVK627E." (PMID 25547136, 2014). "In the present study, we examined the levels of TNF, IL-1β, IL-6, IL-8, and CCL5 in the supernatants of HTNV-infected HUVECs at 48 h post infection using ELISA." (PMID 24714064, 2014). "The number of intracellular WT L. major parasites was unchanged 24 h after infection of the RAW cells and was unaffected by treatment with antibodies to TNF-α or IL-10." (PMID 24732131, 2014). "As the lung and brain showed significant differences in these two H9N2 avian influenza virus strains infection, we chosen to detect the expression patterns of NLRP3 and its related cytokines of IL-1β and TNF-α." (PMID 25547136, 2014). "We examined the levels of TNF-α, IFN-γ, IL-1β, and IL-6 in the kidneys of untreated or EtOH-treated mice and uninfected or infected with Ab at 72 h post-infection." (PMID 24752133, 2014). "Expression of GM-CSF, TNFα, IP10 and IL-1β peaked on day 5 post infection and gradually declined over time." (PMID 24699832, 2014). "Infection of HCMV was found to induce the expression of different cytokines and chemokines among which were TNF-α, IL10, IL-8 and MCP-1." (PMID 23418456, 2013). "In WT mice, levels of TNF-α, IFN-γ and CXCL-1 peaked 24 h after infection and decreased to virtually background levels after 72 h in BAL." (PMID 23991239, 2013). "The kinetics of TNF-α, CXCL1, IFN-γ and IL-6 showed a similar time dependent increasing trend with peak expression at 72h of L2-MHV3 infection." (PMID 24058536, 2013). "Cytokines, such as interferon gamma (IFN-γ) and tumor necrosis factor alpha (TNF-α), secreted by NK cells at early stages of infection mediate inflammatory responses in inflamed tissues and also coordinate with DCs to induce Th1 cell polarization." (PMID 24147080, 2013). "Our studies showed that levels of IL-1, IL-10, MCP-1, TNF-α and IFN-γ following H1N1/144+177 infection were significantly higher compared with H1N1/WT virus, and H1N1/144 and H1N1/177 did not induce all of these cytokine up-regulation but two or three." (PMID 23637827, 2013). "At 9 months after infection with T. cruzi in the dogs previously vaccinated with the pBCSSP4 plasmid, high levels of IFN-γ (1080 pg / mL) were observed and TNF-α was present to a lesser extent." (PMID 23497041, 2013). "This leads to activation, expansion, and functional maturation of Mtb-specific CD4+ T cells that home to the site of primary infection in lung and activates innate immune cells such as macrophages to release IFN-γ and TNF-α to control infection." (PMID 24109479, 2013). "Consistent with the kinetics of expression of the molecular markers of macrophage activation, a significant percentage of CD14+ cells produced TNF-α in the lungs and spleen (10.5% and 9.1% respectively) of CDC1551 infected rabbits at 4 weeks post infection." (PMID 23448601, 2013). "During the course of infection, CD4+ T lymphocytes synthesize cytokines, such as IFN-γ, TNF-α and IL-12, which provide protection to the host, and prevents fungus spread." (PMID 23991239, 2013).
infection (continued). "Some studies have demonstrated that upon infection, H. pylori activates the expression of a number of genes such as CagA, AKT, TNF-α, ATF3, IRX5, IL-6 and IL-8." (PMID 24069310, 2013). "The PMN TM rate was significantly increased after infection with the capsule expressing strain MC58 and TNFα stimulation compared to infection with the unencapsulated mutant strain MC58ΔsiaD, strain α14 and control conditions." (PMID 23448224, 2013). "Drosophila eiger, the sole homolog of the tumor necrosis factor (TNF) and signaling through its receptor wengen (TNF receptor homolog), is suggested to play opposing roles in the fly’s response to infection." (PMID 25437036, 2013). "After infection with hMPV or RSV, the levels of TNF-α were markedly increased compared with the levels in uninfected cells, and the increase in the RSV group was larger than that in the hMPV group (P<0.05)." (PMID 24039959, 2013). "In one study, natural honey significantly increased the tumor necrosis factor-α (TNF-α), interleukin (IL)-1β and IL-6 release from MonoMac-6 cells (and human monocytes) which activate the immune response to infection." (PMID 23997898, 2013). "MDDC matured with CD40L, TNFα, and bacterial lipopolysaccharide (LPS) have a respective, decreasing propensity to support HIV-1 cis infection, while all 3 types of mature MDDC promote efficient trans infection." (PMID 24278768, 2013). "According to the previous data, TNF-α and IL-12/IL-23p40 are produced by different cells and their production depends on different TLR activation during infection." (PMID 23650544, 2013). "Previously, studies examining the lack of activation/active suppression of inflammation by Francisella have been primarily focused on a limited set of well-known mediators, such as TNFα, IL6, IL1β, etc, as a measurement of immune response to infection." (PMID 23690939, 2013). "After 4 weeks of infection, there is a decrease in the levels of antimicrobial peptides (mainly defensins), as well as IFN-γ and TNF-α." (PMID 23555622, 2013). "Compared to the other inbred mouse strains investigated, C3HeB/FeJ mice displayed elevated serum levels of IL-6, TNF-α and extremely high levels of the chemokine CCL2 at 3 and 5 days post infection." (PMID 23617550, 2013). "Real-time PCR was used to determine the difference in proinflammatory cytokine production following infection with the four H1N1 viruses in the mouse lung, including IL-1, IL-10, MCP-1, TNF-α, IFN-γ." (PMID 23637827, 2013). "We calculated the Z-factor (Z’) to be ~0.65 upon infection of HEK293 at MOI 5 for 5 hrs, followed by 18 h of TNF-α stimulation." (PMID 24206648, 2013). "Rage−/− mice did demonstrate reduced TNFα, IL-6 and KC concentrations in BAL fluid 24 hours post infection." (PMID 24342460, 2013). "Both live and UV inactivated virus elicited robust induction of inflammatory cytokines/chemokines such as IL-6, IL-8, TNF-α, and RANTES within 12 h of infection." (PMID 23671700, 2013). "In ELISA, upregulation of TNFα and RANTES production after infection with RSV was inhibited from 0.1 and 1 μg/ml MG132, respectively." (PMID 24058438, 2013). "The anti-H5N1 effect was very likely due to the innate immune recognition of EAP and the secretion of innate immune mediators (IL-6, TNF-α and IFN-γ) before infection." (PMID 24159339, 2013). "As expected from RT-PCR analysis, the secretion of TNF-α from HFF was negligible (open bars), while 150 IU/ml of IFN-β was secreted at 30 h after infection (open bars)." (PMID 24236107, 2013). "In the presence of immune sera and upon infection, TRIM21 also activates a proinflammatory response, resulting in secretion of tumor necrosis factor alpha (TNF-α) and interleukin-6 (IL-6)." (PMID 23596308, 2013). "In ELISA, upregulation of TNFα and RANTES production after infection with RSV was significantly inhibited from 5 μg/ml curcumin." (PMID 24058438, 2013).
infection (continued). "VIPhyb-treatment increased type-I IFN synthesis, numbers of IFN-γ- and TNF-α-expressing NK cells and T-cells, and the numbers of mCMV-M45 epitope-peptide-MHC-I tetramer CD8+ T-cells following mCMV infection." (PMID 23723978, 2013). "In contrast, resistant C57BL/6J mice displayed low serum levels of IFN-γ, TNF-α, IL-6, and CCL2 at both timepoints of infection." (PMID 23617550, 2013). "Most strikingly, almost all the NK cells, regardless of the source (blood and LNs) and subset, lost their capacity to express both IFN-γ and TNF-α, indicating a crippled NK cell cytokine response following MPXV infection." (PMID 24147080, 2013). "On Day 1 and Day 3 post infection, bronchoalveolar lavage fluid (BALF) protein concentration and levels of cytokines including IL6, TNFα, IL1β, Interferon-γ and IL17 were measured." (PMID 23826353, 2013). "In contrast, in mice vaccinated with adjuvanted recombinant H28 alone (H28/H28) we observed the highest production of IL-2 per single cell and the highest frequency of antigen specific TNF-α/IL-2 expressing CD4 T cells pre and post infection." (PMID 23977248, 2013). "In contrast, it is well established that infection and inflammation lead to T cell activation and T cell production of osteoclastogenic cytokines such as RANKL and TNFα (TNF)." (PMID 23935650, 2013). "Based on our findings in the mouse model we suggest that a protective vaccine against infection with M.tb should primarily possess the ability to induce (and maintain) CD4 phenotypes expressing TNF-α/IL-2." (PMID 23977248, 2013). "In both WT and IL-17-/- mice that had recovered from a natural infection (LIC), only low levels of TNFα and IL-12 were produced following in vitro re-stimulation of splenocytes with MOMP." (PMID 24073293, 2013). "Elevated production of cytokines, such as IL-6, TNF-α, and IFN-γ are very important for viral clearance in the early stage of infection by activating the innate immune system." (PMID 24159339, 2013). "Our results suggest, that apoptosis of bystander monocytes occurs after infection with E. coli via internalization of TNFR1, and indicate a relevant role for TNF-α." (PMID 23349721, 2013). "Monocytes are capable of differentiating into dendritic cells (DCs) or into mucosal macrophages during certain infections and of producing inflammatory mediators such as TNF-α (tumor necrosis factor-alpha), nitric oxide, and reactive oxygen species." (PMID 23690669, 2013). "On day 1 after infection, TBBPA exposure significantly increased the TNF-α level in the BALF of RSV-infected mice (P < 0.05 versus control by Student's t-test)." (PMID 24250719, 2013). "In agreement with this, immunization by repeated infection and sub-curative treatment led to high levels of IL-5, IL-10, IL-12, IL-13, IFN-γ, and TNF compared to uninfected mice, where levels were very low or undetectable." (PMID 24180253, 2013). "Experimental studies and patients with PCM indicate that resistance to infection is dependent on the activity of T helper cells and macrophages/monocytes mediated by IFN-γ and TNF-α." (PMID 23991239, 2013). "A strong cell-mediated immune (CMI) inflammatory response, involving tumor necrosis factor-alpha (TNF-α) and interferon-gamma (IFN-γ), is rapidly induced by infection with MTC and is required to protect the infected host against TB." (PMID 23593415, 2013). "Proinflammatory mediators such as IL-6, TNF-α, and MCP-1 increased over time during the course of infection." (PMID 23816343, 2013). "Infection of human monocytes with either UV-inactivated RSV or RSV F protein results in increased production of IL-6, TNF-α and IL-β which is mediated via TLR 4 activation." (PMID 24244872, 2013). "Th1 cells secrete interferon- (IFN-) γ, interleukin- (IL-) 2, and tumor necrosis factor (TNF) and control protection against infection with intracellular microbes." (PMID 23983678, 2013).
infection (continued). "On multivariate regression, comparing cytokine gene expression in health and infection, IL10 (P = 0.02), IL23 (P = 0.01), IL27 (P = 0.01), and TNFα (P = 0.03) were significantly different." (PMID 23935244, 2013). "Using microarray analysis, this study showed up-regulation of toll-like receptors 1, 2, 4, 7, 8, NF-κB, TNF, p38-MAPK, and MHC molecules in human peripheral blood mononuclear cells following infection with Plasmodium falciparum." (PMID 24188121, 2013). "Infection with PAK significantly increased the pro-inflammatory cytokines TNF-α and IL-6 in BAL fluid from SP-A-/- compared to SP-+/+ mice 24 hours after infection." (PMID 24312669, 2013). "By ELISA, upregulation of TNFα and RANTES production after infection with RSV was significantly inhibited from 10 μg/ml salubrinal." (PMID 24058438, 2013). "Infected macrophages secrete cytokines such as Tumor Necrosis Factor- (TNF-) to recruit immune cells (mainly, CD4+ and CD8+ T cells) to the site of infection and prime the activation of effector functions in these cells." (PMID 23580062, 2013). "Tanaka Y found the infection factors of gastrointestinal can activate PAR-2 receptor promoting inflammation medium release, such as IL-6, IL-8 and TNF- α." (PMID 24088410, 2013). "To this end, we stimulated ex vivo purified splenic RFP+ and RFP− pDCs from pDCre x RFP mice with different multiplicities of infection (MOI) of MCMV in vitro and analyzed their TNFα and IFNα production." (PMID 24086137, 2013). "In our assays, IL-12 and TNF-α production was evaluated after BALB/c mice treatment with propolis and infection with L. (V.)braziliensis." (PMID 23762152, 2013). "When monocytes were infected with Mtb, followed by immediate treatment with PZA at 10 or 50 μg/ml, dose-dependent reductions in the levels of pro-inflammatory molecules TNF-α, IL-6, IL-1β and MCP-1, relative to infection alone, were observed." (PMID 24015316, 2013). "Among these mediators are TNF-α, IL-12 and NO, whose release is significantly enhanced by IFN-γ prior to infection and by bovine Natural Killer cells direct contact." (PMID 23691050, 2013). "AD169 showed a similar significant positive correlation for degree of explant infection and MCP-1 and TNF-α expression (p = 0.01 and p = 0.049 respectively)." (PMID 23300810, 2012). "The aim of this study was to characterize the in vivo plasma concentrations of the cytokines TNF-α, IFN-γ, IL-4, IL-10 and the overall role of CD4+ T cells in the development of cytokine levels during a primary infection." (PMID 22533922, 2012). "Our current work suggests a possible role of TNF-α and RANKL in osteoclastogenesis induced by infection with P. gingivalis." (PMID 22723864, 2012). "Specifically, IL-1β and TNF-α signalling are negatively regulated by IL-6 and may compensate for the loss of IL-6, which could explain why IL-6−/− mice were not protected during H1N1pdm infection." (PMID 22679491, 2012). "As before, CD4 TNFα producing cells from uninfected or S. enterica infected mice were mainly CD200R– and decreased during infection." (PMID 22496920, 2012). "Virus-specific CD8+ T cells are recruited to the liver within 4 days of infection and control viral replication through release of cytotoxic molecules and production of cytokines such as IFN-γ and TNF-α." (PMID 22880122, 2012). "Macrophages are known to synthesize and secrete cytokines, including TNF-α, IL1-β, IL-8, IL-6, IFN-γ and others, upon infection with Mtb." (PMID 23029190, 2012). "A major factor determining permissiveness of cells of the myeloid-monocytic lineage for infection with CMV is the state of maturation (and references therein) and it has been demonstrated that TNFα also facilitates maturation of macrophages." (PMID 22952450, 2012). "After intraperitoneal amastigotes inoculation in wild-type and knockout mice for TNF-α, Nod2, Myd88, iNOS, IL-12p40, IL-18, CD4, CD8 and IFN-γ we found that the latter is crucial for controlling infection by G strain amastigotes." (PMID 22509418, 2012).
infection (continued). "In both uninfected and S. mansoni infected mice a proportion of CD4 T cells produced TNFα but these cells were primarily CD200R– and decreased upon infection." (PMID 22496920, 2012). "To determine the role of RANKL and TNF-α in osteoclastogenesis induced by infection with P. gingivalis, we further analyzed the effect of RANKL and TNF-α on osteoclastogenesis in RANKL-primed RAW-D cells in the presence or absence of P. gingivalis." (PMID 22723864, 2012). "In the infection with MT forms cytokine production by CD4+ and CD8+ led to an early production of IFN-γ and only later there was an increase in the production of TNF-α." (PMID 22412949, 2012). "Inflammatory and immunologic responses, mediated by increased levels of TH1-type (TNF-α and IFN-γ) and TH2-type cytokines (IL-10 and IL-6), appear to be important for recovery from infection." (PMID 21912565, 2012). "To further investigate the role of PAR-1 in the local inflammatory response, we determined levels of various cytokines (TNF-α, IL-6, IL-10, IL-12, IFN-γ) and chemokines (MCP-1, MIP-2) in lung homogenates at 6, 24 and 48 hours after infection." (PMID 23270594, 2012). "Inflammatory cytokines, such as IFNγ, interleukin (IL)-6 and TNFα, and the chemokines, CCL2 and CCL5, were highly upregulated in the respiratory tract after infection with 12500 EID50." (PMID 22496659, 2012). "FVB mice showed greatly increased (IL-6, IL-17 and IFN-γ) cytokine and (CXCL1 and MCP-1 and 3) chemokine production profiles early after infection compared to C57BL/6 mice and systemic TNF-α during the hemorrhagic phase of the disease." (PMID 23300439, 2012). "TNF-α is produced by activated mononuclear phagocytes, and the function of TNF-α is to stimulate the recruitment of neutrophils and monocytes to sites of infection." (PMID 23216686, 2012). "those that are highly upregulated only by infection with virulent S. flexneri (CCL4, CCL20, IFN-γ, IL-1β, IL-4, IL-6, IL-8, IL-12/23p40, IL-21, TNF-α, CAP-18, LeukoP and COX-2); ii." (PMID 22675469, 2012). "Genes for the key pro-inflammatory cytokines, like TNFα (two genes in zebrafish: tnfa and tnfb), IL1β, and IL8, and for the anti-inflammatory cytokine IL10 were induced by infection with any of the three pathogens." (PMID 22811714, 2012). "After 30 minutes of S. Typhimurium SL1344(p1C/1) infection the supernatants from ESC derived DCs harbored IL-6, MCP-1 and TNFα." (PMID 23284947, 2012). "The opposite was observed in the infection with BT forms, where initially there was an increase of CD4+ and CD8+ TNF-α, and only later of T-cells IFN-γ+." (PMID 22412949, 2012). "The inflammatory response in the liver showed a similar picture with a significant increase of TNFα and IL10 under infection." (PMID 22815907, 2012). "To further investigate upstream signals of the possible involvement of TNF-α in NMII induced caspase-independent apoptosis, we measured TNF-α release upon infection." (PMID 22303462, 2012). "Infection of RAW-D cells with P. gingivalis stimulated the production of TNF-α, whereas the production of TNF-α by similarly infected RANKL-primed RAW-D cells was markedly down-regulated." (PMID 22723864, 2012). "At high multiplicities of infection (10 MOI), RAW cells up- regulated cell surface expression of TLR4 and secreted significant amounts of TNF-α, MCP-1, IL-10 and IL-12 and NO." (PMID 22642811, 2012). "TNFα expression was 70% lower in both the MSC- and fibroblasts-treated animals after infection (p = 0.02 for MSC-CVB3 and p = 0.045 for Fibro-CVB3 vs. PBS-CVB3)." (PMID 22815907, 2012). "Statistical analysis showed a significant difference in the ESDCs expression at all infection time points for MCP-1 and at 4 hours infection of IL-6 and TNFα compared to undifferentiated ESCs." (PMID 23284947, 2012).